HAGLR (HOXD antisense growth-associated long non-coding RNA)
Synonyms: Mdgt; MIR7704HG; STEEL; HOXD-AS1
Gene: Long non-coding RNA gene on chromosome 2 (176,164,051 to 176,189,421, reverse strand). Ensembl gene ENSG00000224189.
Diseases named in the same sentence as HAGLR in open-access papers:
HAGLR is named in the same sentence as 37 diseases in open-access papers, as found by Europe PMC text mining. Sharing a sentence is not in itself a finding about the gene and the disease. The quoted sentences say what the papers report.
hepatocellular carcinoma (13 papers, 2014 to 2025). A malignant tumor that arises from hepatocytes. "High expression of HAGLR suggested a favorable prognosis for ccRCC, while the expression of HAGLR was upregulated in hepatocellular carcinoma and associated with proliferative and metastatic tumor." (PMID 34386428, 2021). "In conclusion, this study identified and internally evaluated a five-gene metabolic signature (PLPPR1, CNTN3, HOXA10, HAGLR, and ENPP3) associated with immunotherapy response in hepatocellular carcinoma through integrative analysis of multiple transcriptomic datasets." (PMID 41515582, 2025). "In this study, MMP9, SPP1, HAGLR, LINC02202, and RP11-598F7.3 are considered as potential diagnostic biomarkers for hepatocellular carcinoma, and CD4+ memory resting T cells and CD8+ T cells are believed to be involved in HCC immune control." (PMID 35027925, 2022). "Furthermore, through the regulation of SOX4 by HAGLR, HOTAIR is activated and indirectly activates EZH2 and MMP2 (matrix metallopeptidase 2) to facilitate hepatocellular carcinoma metastasis." (PMID 37624034, 2023).
glioma (10 papers, 2019 to 2023). A benign or malignant brain and spinal cord tumor that arises from glial cells (astrocytes, oligodendrocytes, ependymal cells). "To conclude, HAGLR regulates the growth, invasion, and migration of tumor cells through different underlying mechanisms in different types of cancer, such as breast cervical, lung, glioma, gastric, melanoma, ovarian, prostate, and more." (PMID 37624034, 2023).
gastric cancer (9 papers, 2020 to 2024). A primary or metastatic malignant neoplasm involving the stomach. "This indicates HAGLR’s involvement in promoting proliferation and potentially causing cell cycle arrest in gastric cancer cells." (PMID 39172101, 2024). "HAGLR thus represents a potential avenue for the advancement of diagnostic and therapeutic strategies in the context of gastric cancer." (PMID 39172101, 2024). "The present study associates increased levels of HAGLR in gastric cancer tissue with a worsened patient outlook." (PMID 39172101, 2024). "In terms of function, both in vitro and in vivo tests show HAGLR’s role in promoting the growth, invasion, and spread of gastric cancer cells." (PMID 39172101, 2024). "Based on the results, HAGLR expression was significantly upregulated in gastric cancer tissues compared to that in normal tissues." (PMID 39172101, 2024). "RT-PCR determined the levels of HAGLR in several gastric cancer cell lines, including AGS, MKN45, SGC7901, SUN5, and HGC27." (PMID 39172101, 2024). "In summary, HAGLR acts as an oncogenic lncRNA in gastric cancer, contributing to cell malignancy via the HAGLR/miR-20a-5p/E2F1 axis." (PMID 39172101, 2024). "Thereafter, the expression of HAGLR in gastric cancer tissues was determined using RT-PCR." (PMID 39172101, 2024). "Notably, recent findings have pointed to aberrant levels of the lncRNA HAGLR in different cancers, but its specific role in the progression of gastric cancer requires further research." (PMID 39172101, 2024). "In addition, HAGLR sponges, miR-338-3p, could promote 5-Fu resistance in gastric cancer by targeting the LDHA-glycolysis pathway." (PMID 36979404, 2023). "Some lncRNAs affect the glycolysis process by regulating the expression of key enzymes of glycolysis and inducing drug resistance in gastric cancer cell lines; these include, for instance, SNHG7, HAGLR, and SNHG1." (PMID 38927012, 2024). "Among them, LINC01315, AP003392.1, AL590666.2, and HAGLR were highly expressed in gastric cancer tissues, while the expression levels of AP000695.2 and AL161785.1 in gastric cancer tissues were lower than those in normal tissues." (PMID 36979404, 2023). "On the basis of multivariate Cox regression analysis, the analysis also revealed a negative correlation between HAGLR levels and overall survival of gastric cancer patients." (PMID 39172101, 2024). "Gastric cancer tissue analysis via qRT-PCR indicated a reduction in miR-20a-5p, implicating its tumor suppressor role, and its negative correlation with HAGLR." (PMID 39172101, 2024). "In gastric cancer (GC), different lncRNAs are related to drug resistance, by modulating the expression of drug resistance-related genes, such as the oncogenic lncRNAs MACC1-AS1, PVT1 and HAGLR, which are upregulated and promote 5-FU resistance in GC cells." (PMID 36866275, 2023).
neuroblastoma (7 papers, 2014 to 2024). Neuroblastoma (NB) is the most common solid, extracranial childhood tumor. "Interestingly, the greatest difference between CIMP-positive and CIMP-negative tumors was observed for lnc-AC009336.1-2 (commonly called HAGLR), a lncRNA linked to neuroblastoma progression." (PMID 29963224, 2018). "In addition, the RA-induced HAGLR upregulation at 5 and 7 days was observed in another neuroblastoma cell line, SK-N-MC." (PMID 34430707, 2021). "The endogenous miR-130a-3p could not be effectively pulled down by the scramble or sense HAGLR probe, suggesting that HAGLR specifically interacts with miR-130a-3p in neuroblastoma cells." (PMID 34430707, 2021).
non-small cell lung carcinoma (6 papers, 2019 to 2025). A group of at least three distinct histological types of lung cancer, including non-small cell squamous cell carcinoma, adenocarcinoma, and large cell carcinoma. "With inhibition of HAGLR in non-small cell lung cancer cells, cell proliferation and invasion can be suppressed." (PMID 33318305, 2020). "Furthermore, a study quantified the expression levels of 14 lncRNAs (such as HAGLR and TP73-AS1) in cancerous and normal tissues from 92 non-small cell lung cancer (NSCLC) patients using qPCR and constructed a predictive model using machine learning algorithms." (PMID 40332793, 2025). "The present study estimated the usefulness of 14 lncRNAs (HAGLR, ADAMTS9-AS2, LINC00261, MCM3AP-AS1, TP53TG1, C14orf132, LINC00968, LINC00312, TP73-AS1, LOC344887, LINC00673, SOX2-OT, AFAP1-AS1, LOC730101) for early detection of non-small-cell lung cancer (NSCLC)." (PMID 35053601, 2022).
breast carcinoma (5 papers, 2017 to 2025). "Moreover, inhibition of miR-7704 caused an increase in HAGLR expression in both cervical and breast cancer cell lines." (PMID 40943278, 2025). "Importantly, inhibition of mir-7704 caused an increase in HAGLR expression in breast cancer cells, demonstrating negative regulation of the oncogenic lncRNA HAGLR by spliceosomal mir-7704." (PMID 37624034, 2023). "One example is the case of miR-7704, which negatively regulates the expression of lncRNA HAGLR in breast cancer cells." (PMID 40943278, 2025). "The negative regulation of HAGLR by miR-7704 can serve as an overlooked path in controlling aggressive breast cancer." (PMID 33143250, 2020). "While miR-7704 is reported as oncomiR in breast cancer patients, it acts as a tumor suppressor in the SF context, with HAGLR being its nuclear target." (PMID 33143250, 2020). "Although the presence of HAGLR was not previously reported in breast cancer, we demonstrate here that its highest expression level among the three tested cell lines was found in MDA-MB-231." (PMID 33143250, 2020). "When the expression of HAGLR and mir-7704 was analyzed in two breast-cancer-derived cell lines (MCF-7 and MDA-MB-231) and a non-tumorigenic cell line (MCF-10A), which are often used as cellular models for breast cancer, negative correlation was found between the expression of HAGLR and mir-7704." (PMID 37624034, 2023).
cervical cancer (4 papers, 2021 to 2025). A primary or metastatic malignant neoplasm involving the cervix. "Further support for our results and hypothesis comes from survival curve analysis of HAGLR in breast and cervical cancer based on gene expression levels, showing that low levels of HAGLR are associated with patients’ survival." (PMID 37624034, 2023). "It was demonstrated that mir-7704 negatively regulates the expression of the oncogenic HAGLR in breast and cervical cancer cells." (PMID 37624034, 2023). "Here, we highlight a new player, namely spliceosomal mir-7704, and the crosstalk between HAGLR and spliceosomal mir-7704 as a novel target for the diagnosis and therapeutics of breast and cervical cancer." (PMID 37624034, 2023). "We thus propose the use of modified oligos, which mimic the effect of mir-7704 to suppress the expression of HAGLR in breast and cervical cancer." (PMID 37624034, 2023). "HAGLR was also found to upregulate zinc finger E-box binding homeobox 1 (ZEB1) through binding with miR-130a-3p to promote resistance to cisplatin (chemotherapy medication used to treat several types of cancers) in cervical cancer." (PMID 37624034, 2023). "Furthermore, overexpression of miR-7704 decreased HAGLR expression in a cervical cancer cell line." (PMID 40943278, 2025).
esophageal cancer (4 papers, 2020 to 2022). A primary or metastatic malignant neoplasm involving the esophagus. "HAGLR was reported to regulate the proliferation and metastasis of lung cancer and esophageal cancer, respectively." (PMID 35198013, 2022). "HAGLR was increased in esophageal cancer and acted as a sponge of miR-143-5p, which promoted EMT (epithelial-mesenchymal transition) associated genes expression and migration of esophageal cancer cells." (PMID 34375306, 2021).
lung cancer (4 papers, 2017 to 2022). A malignant neoplasm involving the lung. "HAGLR is a novel lncRNA mainly studied in lung cancer and serous ovarian carcinoma." (PMID 34375306, 2021).
lymph node metastasis (4 papers, 2021 to 2024). "Further investigations established a correlation between HAGLR expression and adverse clinical features like lymph node metastasis, larger tumors, advanced TNM stages, and poor patient prognosis in GC." (PMID 39172101, 2024). "Moreover, plasma exosomal lncRNA HAGLR can be an available indicator for predicting NSCLC-related recurrence and metastasis because of the positive correlation between the expression of exosomal lncRNA HAGLR and lymph node metastasis and TMN stage 139." (PMID 37476194, 2023).
colon adenoma (1 paper, 2018). An adenoma that arises from the colon. "We thus compared the expression of HAGLR in tumor versus normal tissues in the colon adenoma dataset downloaded from The Cancer Genome Atlas (TCGA) database." (PMID 29963224, 2018).
colon cancer (1 paper, 2023). "Similarly, high HAGLR expression in colon cancer accelerates its progression." (PMID 37081965, 2023).
lung adenocarcinoma (1 paper, 2024). A carcinoma that arises from the lung and is characterized by the presence of malignant glandular epithelial cells. "The lncRNA known as HAGLR, implicated in various cancers such as esophageal and lung adenocarcinoma, is currently being investigated for its role in GC proliferation and migration." (PMID 39172101, 2024).
osteoarthritis (1 paper, 2023). A noninflammatory degenerative joint disease occurring chiefly in older persons, characterized by degeneration of the articular cartilage, hypertrophy of bone at the margins and changes in the synovial membrane. "We also revealed the correlation between lncRNA HAGLR and miR-130a-3p in osteoarthritis, control-siRNA, HAGLR-siRNA, inhibitor control, or miR-130a-3p-inhibitor were transfected into CHON-001 cells." (PMID 36918905, 2023). "According to these observations, we concluded that lncRNA HAGLR negatively regulated miR-130a-3p level in osteoarthritis." (PMID 36918905, 2023). "Our results suggest that lncRNA HAGLR may play a role in osteoarthritis by regulating the expression of miR-130a-3p." (PMID 36918905, 2023). "Our findings suggested that lncRNA HAGLR and miR-130a-3p might function in osteoarthritis." (PMID 36918905, 2023).
cancer (31 papers, 2014 to 2025). A tumor composed of atypical neoplastic, often pleomorphic cells that invade other tissues. "The lncRNA HOXD antisense RNA 1 (HOXD-AS1), also called HAGLR (HOXD antisense growth-associated long non-coding RNA) is strongly related to cancer." (PMID 32756406, 2020). "For several remaining top genes, functional validation pinpointed a causal role in carcinogenesis, but in specific cancers other than KIRC (SCIN, HAGLR, GSTP1)." (PMID 41188181, 2025). "HAGLR is HOXD antisense growth-associated LncRNA, which has been testified to be associated with diversified diseases, covering cancer, neurodegenerative diseases, heart disease, and bone disease." (PMID 37752532, 2023). "As such, HAGLR and LINC01315 have become diagnostic and prognostic markers for various cancers due to their close relationship with malignant tumors." (PMID 36979404, 2023). "Five metabolism-related lncRNAs (HAGLR, H19, AC092718.4, FAM181A-AS1, and AC007383.2) are associated with cancer." (PMID 36343057, 2022). "In 40 samples of patients diagnosed with TNBC, lncRNA HAGLR was highly expressed in TNBC cancer compared with para-carcinoma tissues." (PMID 34375306, 2021). "HAGLR is a lncRNA transcribed from the HOXD cluster on human chromosome 2 that is upregulated in multiple cancers, including colon cancer 91, hepatocellular carcinoma 92 and BC 93, and is closely related to progression and unfavorable prognosis." (PMID 34803512, 2021). "Among them, HOTAIRM1 and HAGLR showed relatively higher expression levels in all the cancer types than the other HOXATs." (PMID 34805277, 2021). "HAGLR has been shown to play a role in the development and progression of these cancers, and its expression level was correlated with cancers’ clinical features." (PMID 33143250, 2020). "HAGLR also has the ability to act as an miRNA decoy to promote cancer progression." (PMID 37624034, 2023). "The results obtained indicated that elevated HOTTIP and HAGLR expression levels could predict poor prognosis in cancer patients, suggesting that HOTTIP and HAGLR might serve as novel prognostic biomarkers for cancer." (PMID 34805277, 2021). "The study also found that HAGLR, as a competitive endogenous RNA of miR‐143‐5p, increases the expression of LAMP3, thereby promoting the proliferation, invasion, and migration of cancer cells." (PMID 35028969, 2022).
tumor (27 papers, 2014 to 2026). "The high expression of HAGLR was positively correlated with the high detection rate of circulating tumor cells, suggesting the presence of a later tumor stage, which is clearly associated with poor prognosis." (PMID 38052753, 2023). "HAGLR (also known as HOXD-AS1), a long non-coding RNA, has been implicated in transcriptional regulation linked to tumor progression, epithelial–mesenchymal transition, and immune suppression, suggesting a role in shaping immunosuppressive tumor states that may limit immunotherapy efficacy." (PMID 41515582, 2025). "In our work, bioinformatics and dual-luciferase assays revealed that HAGLR binds to miR-20a-5p, which generally acts as a tumor suppressor." (PMID 39172101, 2024). "The mice injected with the shRNA-expressing HGC27 cells developed markedly smaller tumors, both in terms of size and weight, as compared to the control group, highlighting HAGLR’s role in promoting tumor growth." (PMID 39172101, 2024). "Further histological analysis with H&E staining supported the inhibitory effect of HAGLR knockdown on tumor formation, and immunohistochemical analysis confirmed decreased Ki-67 proliferation marker levels in the HAGLR-suppressed tumors." (PMID 39172101, 2024). "To assess HAGLR’s impact on tumor growth in vivo, we established a mouse model by injecting female nude mice with HGC27 cells that either contained shRNA targeting HAGLR or a control sequence." (PMID 39172101, 2024). "Other studies have argued for an oncogenic role of HAGLR, as it can act as a competing endogenous RNA for miR-217, promoting tumor progression in CRC." (PMID 36674824, 2023). "In lung adenocarcinoma (LUAD), lncRNA HAGLR was identified as a tumor suppressor by recruiting DNMT1 to the promoter of E2F1 to inhibit tumor growth." (PMID 35292092, 2022). "Mounting evidence suggests that high expression of HAGLR is related to clinicopathological features such as tumor size, lymph node metastasis, differentiation, TNM stage, and prognosis." (PMID 35027925, 2022). "In vivo tumorigenesis experiments indicated HAGLR accelerated tumor growth via miR-335-3p/WNT2 axis." (PMID 34375306, 2021). "We have thus identified HAGLR as the nuclear target of miR-7704, which acts as a tumor suppressor in the spliceosomal context." (PMID 33143250, 2020). "HAGLR was found to be downregulated in tumor samples (n = 155) as compared to normal tissue (n = 19)." (PMID 29963224, 2018). "Thus, the spliceosomal miR-7704 acts as a tumor-suppressor gene, and the oncogenic lncRNA HAGLR is its nuclear target." (PMID 40943278, 2025). "Moreover, the inhibition of miRNA-7704 resulted in reduced expression levels of HAGLR, indicating that miRNA-7704 targets HAGLR as a tumor suppressor." (PMID 38577021, 2024). "They described miR-7704 as a tumor suppressor and identified the HAGLR gene as its nuclear target." (PMID 37168377, 2023). "The tumor formation experiment in nude mice was used to explore the function of HAGLR in vivo." (PMID 34375306, 2021). "We observed that five genes (HAGLR, ADAMTS9-AS2, TP73-AS1, LINC00261, and LINC00312) were downregulated in tumor vs. normal lung tissue (NSCLC, LUAD, LUSC); however, the expression was lifted in LUAD tumors in comparison to LUSC tumors." (PMID 35053601, 2022). "In LUAD tumor, compared to LUSC tumor, we found the increased expression of 8 lncRNAs (HAGLR, ADAMTS9-AS2, LINC00261, LINC00673, MCM3AP-AS1, LINC00312, TP73-AS1, AFAP1-AS1) and decreased expression of 2 lncRNA (LOC344887 and SOX2-OT)." (PMID 35053601, 2022). "In vitro studies revealed that four selected lncRNAs including, CDKN2B-AS1, LOC102724156, HAGLR and FAM120AOS were significantly increased in the presence of in optimum concentration of Ag@Glu/TSC and decreased in tumor tissues versus adjacent normal tissues." (PMID 33292233, 2020).
digestive system tumors (2 papers, 2020 to 2023). "Many studies have indicated that HAGLR exerts an unfavorable effect on the prognosis and treatment of gastrointestinal tumors." (PMID 37081965, 2023).
HAGLR also shares sentences with these, for which no sentence is quoted: ovarian carcinoma (8 papers); prostate carcinoma (7); colorectal cancer (6); bladder cancer (5); liver cancer (5); melanoma (3); osteosarcoma (3); colorectal adenoma (2); metastatic tumor (2); Cirrhosis (1); epithelial ovarian tumors (1); glioblastoma (1); heart disease (1); infection (1); metastatic cancer (1); myocardial ischemia (1); neurodegenerative disease (1); primary immunodeficiency (1); serous ovarian carcinoma (1); triple-negative breast carcinoma (1).